GOLPH3 (golgi phosphoprotein 3)
Diseases named in the same sentence as GOLPH3 in open-access papers (continued):
Sharing a sentence is not in itself a finding about the gene and the disease.
benign skin nevus (1 paper, 2016). "Only in four cases (all were diagnosed as compound benign skin nevus) scanty immunoexpression of GOLPH2 and GOLPH3 in benign melanocytes and stromal compartment of the nevi was observed." (PMID 27706081, 2016).
bone metastasis (1 paper, 2012). Transfer of a neoplasm from its primary site to bones. "Moderate /intense expression of GOLPH3 was associated with androgen independence (P = 0.012), higher Gleason score (P = 0.017), bone metastasis (P = 0.024), higher baseline prostate-specific antigen (PSA) (P = 0.038), and higher PSA nadir (P = 0.032)." (PMID 23006319, 2012). "In this research study, it was found that the incidence of Gleason score, PSA nadir, baseline PSA, and positive bone metastasis was higher in patients detected with moderate/intense GOLPH3 expression." (PMID 23006319, 2012).
brain cancer (1 paper, 2023). A primary or metastatic malignant neoplasm affecting the brain. "The retromer subdomain VPS35 interacts with Golgi phosphoprotein 3 (GOLPH3) to support Evi/Wls recycling and Wnt signalling, thus promoting brain cancer." (PMID 36763105, 2023).
breast adenocarcinoma (1 paper, 2019). "Moreover, the knocking down of GOLPH3 in the cell line MDA-MB-231 of human breast adenocarcinoma results in an apparent opposite change in cell morphology, i.e., from a mesenchymal to a more amoeboid phenotype." (PMID 30779783, 2019).
cutaneous melanoma (1 paper, 2016). A primary melanoma arising from atypical melanocytes in the skin. "We believe that no clinicopathological analysis of GOLPH3 expression in tissue specimens from patients with cutaneous melanoma has been published so far." (PMID 27706081, 2016).
diabetes (1 paper, 2022). "In our study, by molecular docking and virtual screening, we found that bromocriptine could inhibit the expression of Golph3, which mediates the HG induced Golgi stress, thus exert its protective function against diabetes neuroinflammation." (PMID 36378718, 2022). "Our study elucidated that HG induced Golgi stress was mediated by NLRP3/Vps35/Golph3/Vimentin pathway, inhibition of NLRP3 and Golph3 by selected molecular inhibitors zafirlukast and bromocriptine could suppress neuro-inflammation and Golgi stress thus ameliorate diabetes cognitive decline." (PMID 36378718, 2022). "Whether the Golph3 pathway plays a role in the pathophysiology of diabetes neuroinflammation has not been studied." (PMID 36378718, 2022).
endotoxemia (1 paper, 2023). "In summary, we demonstrated that GOLPH3 promotes acute liver and kidney injury induced by endotoxemia, associated with Golgi stress, inflammatory responses, and apoptotic cell death." (PMID 37479687, 2023). "Here, we found that upregulation of GOLPH3 was associated with endotoxemia-induced acute liver and kidney injury." (PMID 37479687, 2023). "In endotoxemia-induced acute lung injury, GOLPH3 is highly increased and associated with oxidative stress, inflammation, and apoptosis; which were alleviated by activation of heme oxygenase-1 through reduction of Golgi fragmentation and GOLPH3 expression." (PMID 37479687, 2023). "This study investigated whether GOLPH3 is associated with endotoxemia-induced hepatic and renal injury." (PMID 37479687, 2023). "Importantly, downregulation of GOLPH3 attenuated Golgi stress and inflammatory responses in an in vitro model of endotoxemia, suggesting a clear association of GOLPH3 with endotoxemia-induced liver and kidney dysfunction." (PMID 37479687, 2023). "Recent studies have demonstrated that GOLPH3 expression is upregulated in oxygen-glucose deprivation and reoxygenation injury and endotoxemia-induced lung injury." (PMID 37479687, 2023). "The results demonstrated that LPS-induced endotoxemia increased GOLPH3 expression, followed by the induction of Golgi stress and excessive pro-inflammatory mediators (Tnfα, IL-6, and IL-1β) in mice." (PMID 37479687, 2023). "In conclusion, GOLPH3 is a novel therapeutic target in endotoxemia-induced acute liver and kidney injury by regulating the Golgi stress response." (PMID 37479687, 2023). "This study investigated the effect of GOLPH3 on NF-κB activation in the endotoxemia-induced liver and kidney injury." (PMID 37479687, 2023). "In this study, we investigated the role of GOLPH3 in the development and progression of endotoxemia-induced ALI and AKI." (PMID 37479687, 2023). "In this study, LPS-injected mice significantly upregulated GOLPH3 protein and mRNA expression in the liver and kidney, which was strongly correlated with endotoxemia-induced liver and kidney dysfunction." (PMID 37479687, 2023). "Golgi phosphoprotein 3 (GOLPH3), linking Golgi membranes to the cytoskeleton, has been identified as an important oncogenic regulator; however, its role in endotoxemia-induced acute liver and kidney injury remains elusive." (PMID 37479687, 2023). "Taken together, GOLPH3 plays a crucial role in the development and progression of acute liver and kidney injury by promoting Golgi stress and increasing inflammatory response and apoptosis, suggesting GOLPH3 as a potential therapeutic target for endotoxemia-induced tissue injury." (PMID 37479687, 2023).
Fibroadenoma (1 paper, 2017). A benign tumor of the breast characterized by the presence of stromal and epithelial elements. "We found that GOLPH3 expression in tumor tissue was higher than that in adjacent noncancerous tissue (ANT) and fibroadenoma." (PMID 29285241, 2017).
gastrointestinal carcinoma (1 paper, 2014). "Similarly, the chemosensitivity of CRC cells to paclitaxel, a chemotherapy agent widely used in advanced gastrointestinal carcinoma, was also found to be modulated by GOLPH3." (PMID 24444035, 2014).
injury (1 paper, 2023). Damage inflicted on the body as the direct or indirect result of an external force, with or without disruption of structural continuity. "In the present study, we showed that upregulation of GOLPH3 was strongly associated with Golgi stress and inflammatory response in the development and progression of acute liver and kidney injury." (PMID 37479687, 2023).
invasive breast carcinoma (1 paper, 2019). A carcinoma that infiltrates the breast parenchyma. "The present study aimed to retrospectively evaluate the pathological value of FAP-a and GOLPH3 in predicting the recurrence or progression of DCIS to invasive breast cancer." (PMID 31921678, 2019). "The combination of FAP-a and GOLPH3 in predicating the recurrence or progression of DCIS into invasive breast cancer was specifically examined." (PMID 31921678, 2019). "FAP-a and GOLPH3 serve as novel markers in predicting the recurrence or progression of DCIS into invasive breast cancer." (PMID 31921678, 2019). "We have shown here that the presence of FAP-a in stromal fibroblasts and GOLPH3 in carcinoma cells are reliable biomarker of DCIS recurrence and progression into invasive breast cancer." (PMID 31921678, 2019). "To this end, we specifically examined the correlation between FAP-a and GOLPH3 expression, their clinico-pathological values in predicting the recurrence or progression of DCIS into invasive breast cancer." (PMID 31921678, 2019). "The study demonstrated that the overexpression of FAP-a in stromal fibroblasts and GOLPH3 in carcinoma cells are highly predictive of DCIS recurrence and progression into invasive breast cancer." (PMID 31921678, 2019). "Thus, we identified that FAP-a and GOLPH3 might potentiate as a reliable biomarker for predicting the DCIS recurrence and progression of DCIS into invasive breast cancer." (PMID 31921678, 2019). "Among the 132 GOLPH3 positive DCIS patients, 44 of them underwent a recurrence to DCIS, 48 recurred and progressed into invasive breast cancer, while the remaining 37 cases did not experienced no recurrence." (PMID 31921678, 2019).
lung adenocarcinoma (1 paper, 2021). A carcinoma that arises from the lung and is characterized by the presence of malignant glandular epithelial cells. "However, the potential biological regulation network of GOLPH3 in lung adenocarcinoma (LUAD) remains to be determined." (PMID 34497755, 2021). "The kinases and transcription factors—target networks of GOLPH3 in lung adenocarcinoma." (PMID 34497755, 2021).
metastasis (1 paper, 2017). The spread or migration of cancer cells from one part of the body (where they first appeared) to another. "We analyzed the correlation between GOLPH3 expression and age, T classification (tumor invasion depth), N classification (lymphatic metastasis), M classification (distant metastasis), molecular subtype, and surgery type." (PMID 29285241, 2017).
microcephaly (1 paper, 2019). A congenital or acquired developmental disorder in which the circumference of the head is smaller than normal for the person's age and sex. "The central role played by GOLPH3 upon energetic stress, its implication in cell survival following DNA damage and its involvement in the apical identity of aRGCs during neocortical development, suggest that GOLPH3-controlled pathways may be strongly associated with microcephaly." (PMID 31832602, 2019).
Miscarriage (1 paper, 2023). A pregnancy that ends at a stage in which the fetus is incapable of surviving on its own, defined as the spontaneous loss of a fetus before the 22th week of pregnancy. "However, besides the copy number variants of GOLPH3 observed in idiopathic recurrent miscarriage, very few studies reported the association between GOLPH3 and endometrial decidualization." (PMID 36967990, 2023).
myopia (1 paper, 2010). "Six candidate genes CDH6, CDH10, CDH12, PDZD2, GOLPH3, and ZFR at this high myopia locus were selected on the basis of their function to screen for gene mutations by re-sequencing." (PMID 21042559, 2010).
prostate tumors (1 paper, 2022). "Attenuation of hsa-miR-133a-3p and miR-1-3p expression by promoter methylation in prostate tumors may enhance PCa development, in part by targeting GOLPH3 and JUP." (PMID 36387263, 2022). "We found that GOLPH3 and JUP expression was significantly increased in primary prostate tumors compared to NAT." (PMID 36387263, 2022).
Sepsis (1 paper, 2025). Sepsis is defined as life-threatening organ dysfunction caused by a dysregulated host response to infection. "Golgi phosphoprotein 3 (GOLPH3) was a downstream gene of miRNA-577 and was highly expressed in AKI patients with sepsis." (PMID 40083322, 2025).
triple-negative breast carcinoma (1 paper, 2015). An invasive breast carcinoma which is negative for expression of estrogen receptor (ER), progesterone receptor (PR), and human epidermal growth factor receptor 2 (HER2). "Remarkably Salem and coauthors demonstrated that overexpression of GOLPH3 in MDA-MB-231 triple-negative breast cancer cells promotes mitochondrial biogenesis as revealed by a 2–3-fold increase in Mito Tracker activity." (PMID 25691054, 2015). "In the triple-negative breast cancer cell line, MDA-MB-231 cells, cell-cell adhesion is impaired and cell migration is promoted by overexpression of wild type GOLPH3 but not by the R90L mutant version of this protein." (PMID 25691054, 2015).
cancer (104 papers, 2010 to 2026). A tumor composed of atypical neoplastic, often pleomorphic cells that invade other tissues. "Multiple studies have reported the upregulation of GOLPH3 in various cancers, strongly associating it with tumor advancement, metastasis, and patient prognosis." (PMID 38828452, 2024). "Cell cycle regulation, a fundamental process tightly linked to cancer development, is significantly impacted by GOLPH3 participation." (PMID 38828452, 2024). "GOLPH3, in turn, has been implicated in vesicle trafficking and signal transduction, essential for cancer cell proliferation and metastasis." (PMID 38828452, 2024). "Of these proteins, GM130 and GOLPH3 are associated with cancer cell invasion while golgin-160 and golgin-97 are involved with growth factor receptor transport as well as protein glycosylation and protein glycosylation processes, respectively." (PMID 37508488, 2023). "Endometrial decidualization is a biological process coupled with cell proliferation, extracellular matrix organization, and cell invasion, which are also observed in cancer development and associated with the functions of GOLPH3 in cancers." (PMID 36967990, 2023). "Golgi-specific proteins also can act as oncoproteins when their expression is upregulated or their function is altered in cancer cells—GOLPH3’s increased secretion causes exocytosis of pro-metastatic factors." (PMID 37296620, 2023). "In turn, the synergistic GOLPH3-myosin 18a relationship is necessary for DNA damage to induce Golgi fragmentation, which itself is a prerequisite for most mutations and cancers." (PMID 37051238, 2023). "Overexpression of human GOLPH3 correlates with poor prognosis in several cancer types and is associated with enhanced signaling downstream of mTOR (mechanistic target of rapamycin)." (PMID 36435842, 2022). "Recent studies report that GOLPH3 is implicated in progression of various cancers and affects disease prognosis." (PMID 35073936, 2022). "Several proteins involved in spermatocyte cytokinesis have been implicated in cancer pathogenesis, such as GOLPH3, myosin II and anillin." (PMID 35203341, 2022). "Knockdown studies showed that GOLPH3 repression causes Golgi fragmentation and prevents cancer cell spreading." (PMID 35563790, 2022). "A novel combination of GOLPH3 inhibitor and radiotherapy offers an exciting therapeutic strategy to overcome the radioresistance of cancer and reduce the risk of secondary cancer caused by the RIBE." (PMID 36358544, 2022). "Gene set enrichment analysis (GSEA) of a publicly available NSCLC dataset (NCBI/GEO/GSE75037) showed that GOLPH3 expression was positively associated with metastasis and cancer stem cell-like phenotype." (PMID 34671013, 2021). "The upregulation of the GA-resident proteins GOLPH2 and GOLPH3 is associated with GA orientation and have been linked with tumorigenesis and cancer progression by promoting cell migration, invasion and adhesion as well as mitochondrial biogenesis." (PMID 31693977, 2020). "Compelling evidence indicates that GOLPH3 expression correlates with cancer-associated phenotypes and with poor survival in different solid tumors." (PMID 32023813, 2020). "Overexpression of GOLPH3 in cancer cell lines of different tissues causes an increase in the activation of the PI3K/AKT/mTOR oncogenic signaling pathway." (PMID 33238647, 2020). "This suggested possible explanations to the tumorigenic effect of GOLPH3, because deregulation of mTOR signaling is associated to tumor progression and cancer." (PMID 30779783, 2019). "Golgi phosphoprotein 3 (GOLPH3), a newly recognized oncogene, is associated with tumor growth, metastasis, and poor prognosis in several types of cancer." (PMID 28332316, 2017). "GOLPH2 and GOLPH3 are Golgi-related proteins associated with aggressiveness and progression of a number of cancers." (PMID 27706081, 2016).
cancer (continued). "Golgi phosphoprotein 3 (GOLPH3) has been implicated in the development of carcinomas in many human tissues, and is currently considered a bona fide oncoprotein." (PMID 27123979, 2016). "Previous studies showed the presence of GOLPH3 as an oncogene encoded by a gene on chromosome 5p13 in several human cancers including breast, oral tongue, prostate, kidney and liver cancers." (PMID 28983350, 2015). "Since tetraploidy has been associated with cancer initiation and progression these findings suggest novel paths that can link the oncogene GOLPH3 to malignancy." (PMID 25691054, 2015). "Because cytokinesis failures have been associated with premalignant disease and cancer, our studies suggest novel insight into molecular circuits involving the oncogene GOLPH3 in cytokinesis." (PMID 24786584, 2014). "Because cytokinesis failures have been associated with premalignant disease and cancer our findings suggest novel insight into molecular circuits that involve the oncogene GOLPH3 in cytokinesis." (PMID 24786584, 2014). "Additionally, the oncogenic activity of GOLPH3 has been linked with enhanced signaling downstream of mechanistic target of rapamycin (mTOR) in several cancer types." (PMID 40136688, 2025). "In turn, GOLPH3-dependent defects have been associated with malignant phenotypes in cancer cells." (PMID 40136688, 2025). "Furthermore, GOLPH3 is associated with DNA replication, another crucial step in cancer cell proliferation." (PMID 38828452, 2024). "Based on these findings, we hypothesized that GOLPH3 plays a crucial role in communication between cancer cells and tumor-associated macrophages (TAMs)." (PMID 38828452, 2024). "Overexpression of GOLPH3 has been demonstrated in several human solid cancers, including breast cancer, glioblastoma, gastric cancer, and colorectal cancer, and is associated with cancer progression." (PMID 37293129, 2023). "However, the role and mechanism of GOLPH3 on modulating cancer-associated intercellular signaling communication to promote angiogenesis and resistance of sorafenib has not yet been explored." (PMID 35073936, 2022). "Our findings suggest novel molecular targets associated with GOLPH3 that might be relevant for therapeutic intervention in cancers and other human diseases." (PMID 34571985, 2021). "Importantly, in the context of cancer pathogenesis, human GOLPH3 function has been associated with enhanced AKT/mTOR signaling, although the precise biochemical basis for its activity remains to be determined." (PMID 34571985, 2021). "Additionally, punicalagin compromised the invasive potential of cancer cells through the attenuation of β-catenin pathway or down-regulation of GOLPH3 associated with epithelial to mesenchymal transition reduction." (PMID 34444893, 2021). "As many proto-oncogenes encode glycosylated proteins involved in tumor cell proliferation, adhesion, invasion, migration, immune recognition and signal transduction 37, GOLPH3 may be associated with tumorigenesis and malignant biological behavior of cancer." (PMID 31737112, 2019). "Interestingly, our study elucidated that the presence of GOLPH3 in carcinoma cells is also specifically associated with DCIS recurrence." (PMID 31921678, 2019). "Moreover, upregulation of GOLPH2 and GOLPH3 in cancer cells was associated with shorter DFS and CSOS." (PMID 27706081, 2016). "Moreover high GOLPH3 levels have been associated with poor survival in many cancers, providing a prognostic biomarker of tumor progression." (PMID 25691054, 2015). "Because, in most solid tumors, the upregulation of GOLPH3 is associated with the enhanced activation of both mTORC1 and mTORC2, it will be important to further dissect the potential interplay of GOLPH3 with mLST8 in mTORC2 signaling in a broad set of cancer contexts." (PMID 40136688, 2025).